LIPH (lipase H)
Diseases named in the same sentence as LIPH in open-access papers:
LIPH is named in the same sentence as 33 diseases in open-access papers, as found by Europe PMC text mining. Sharing a sentence is not in itself a finding about the gene and the disease. The quoted sentences say what the papers report.
breast carcinoma (6 papers, 2017 to 2025). "We found that LIPH expression was associated with metastasis in lymph nodes and distant organs (P = 0.025), resulting in poor survival among breast cancer patients (P = 0.027)." (PMID 32618099, 2020). "Finally, LIPH‐positive breast cancer in patients with TNBC was associated with a significantly shorter disease‐free survival (DFS) compared to LIPH‐negative breast cancer (P = 0.0273)." (PMID 32618099, 2020). "Studies indicated that LIPH had a higher expressed level in breast tumor tissue, and it affected the distant metastasis of breast cancer by regulating CAPN2 and paxillin." (PMID 37745080, 2023). "ATGL is not the only lipase upregulated in breast cancer cells, where intracellular Lipase member H (LIPH) was also highly expressed in cancer cells from breast cancer patients." (PMID 35912266, 2022). "LIPH has also been found to have the ability to increase the metastatic ability of breast cancer cells." (PMID 35912266, 2022). "Although the mechanism of LIPH in tumorigenesis is unclear, numerous studies have shown that LIPH participates in tumor metastasis, and the expression level of LIPH is a predictive factor in breast cancer." (PMID 34732125, 2021). "We have previously shown that lipase H is differentially expressed in patients with breast cancer and is related to poor prognosis of breast cancer." (PMID 32618099, 2020). "To understand the role of LIPH in breast cancer metastasis, we further evaluated the expression of LIPH in 30 advanced breast cancer specimens with both primary and metastatic focus." (PMID 32618099, 2020). "LIPH enhances breast cancer cell mobility, potentially facilitating metastasis." (PMID 40426878, 2025). "We investigated whether LIPH plays an important role in the maintenance of CSCs and promotes metastasis in breast cancer cells." (PMID 32618099, 2020). "The role of LIPH in breast cancer cell migration and invasion was also evaluated." (PMID 32618099, 2020). "Although the involvement of LIPH in breast cancer cell proliferation has been previously proposed, its exact pathogenetic role remains largely unknown." (PMID 32618099, 2020). "Thus, LIPH silencing decreased the population of breast cancer stem‐like cells." (PMID 32618099, 2020). "We further analysed LIPH expression and the frequency of CD44+/CD24− cells in 139 specimens from patients with different molecular types of breast cancer by immunofluorescence." (PMID 32618099, 2020). "Thus, LIPH expression stimulates breast cancer cell mobility and may be crucial for metastasis." (PMID 32618099, 2020). "Thus, LIPH lipase‐dependent functions are required for LIPH‐induced enhancement of invasiveness, stemness, and basal/EMT features of breast cancer cells." (PMID 32618099, 2020). "After stratification of these specimens based on LIPH expression, we found that the percentage of CD44+/CD24− CSCs in LIPH + TNBC specimens was significantly higher than the percentage in the corresponding LIPH‐ breast cancer." (PMID 32618099, 2020).
hypotrichosis (5 papers, 2014 to 2025). A congenital condition, usually due to genetic aberrations, that is characterized by a lack of hair growth on the head and/or body. "Hypotrichosis is an uncommon type of alopecia (hair loss) characterized by coarse scalp hair caused by the reduced or fully terminated activity of the Lipase-H (LIPH) enzyme." (PMID 37375751, 2023). "In the present research, we used in silico methods to perform various analyses of the nsSNPs, since a mutation in the LIPH gene is accountable for autosomal recessive hypotrichosis." (PMID 37375751, 2023). "Hypotrichosis (hair loss) is caused by either LIPH or LPAR6 gene mutations." (PMID 37375751, 2023). "Note that minoxidil is labeled for androgenetic alopecia; its use for LIPH-associated ARWH and congenital hypotrichosis is off-label." (PMID 41426600, 2025). "The LIPH gene-related disorder is woolly hair, or hypotrichosis (OMIM 604379)." (PMID 37375751, 2023).
pancreatic cancer (4 papers, 2023 to 2025). "The expression of LAMA3 and LIPH was markedly increased within pancreatic tumour tissues and was linked to advanced stage and poor prognosis." (PMID 37745080, 2023). "Similarly, LIPH also exhibited higher expression in pancreatic tumour tissues and was linked to the advanced stage and poor prognosis." (PMID 37745080, 2023). "Utilizing GEPIA platform, the mRNA expression of LAMA3 and LIPH between pancreatic tumour and normal tissues was investigated." (PMID 37745080, 2023). "Taken together, these data indicate that LIPH is an unfavorable prognostic factor for pancreatic cancer and is highly correlated with disease progression." (PMID 37990271, 2023). "Taken together, these data indicated that LPA produced by LIPH promoted pancreatic cancer cell proliferation by enhancing glycolysis in vitro and in vivo." (PMID 37990271, 2023). "Since mutant KRAS is a critical mediator of pancreatic cancer metabolism, we evaluated the association between KRAS mutations and LIPH expression." (PMID 37990271, 2023). "Finally, we used single-cell analysis to further reveal the cell subpopulation composition in pancreatic tumour microenvironment, as well as the relative expression of LIPH and LAMA3 in different cell subpopulations." (PMID 37745080, 2023). "Thus, instead of direct inhibition, targeting LIPH in pancreatic cancer cells might be a possible therapeutic avenue." (PMID 37990271, 2023). "Therefore, we speculate that LIPH is mainly involved in the regulation of pancreatic cancer (PC) cell proliferation and self-renewal." (PMID 37990271, 2023). "To study the effect of LIPH on PDAC, we examined the expression level of LIPH in eight pancreatic cancer cell lines at the mRNA and protein levels, with the highest expression in CFPAC-1 cells and the lowest expression observed in MIA PaCa-2 cells." (PMID 37990271, 2023). "Pan-cancer analysis using the expression of 28 tumors and the Cancer Cell Line Encyclopedia (CCLE) revealed that LIPH was highly expressed in PDAC tissues and cell lines originating from pancreatic cancer compared to other tumor types." (PMID 37990271, 2023).
hair disorders (3 papers, 2024 to 2025). "Recent genetic studies on human hair disorders have demonstrated the essential role of LIPH-LPA-LPAR6 signaling in hair shaft development." (PMID 40417239, 2025). "LIPH, which encodes an endothelial lipase, regulates lipid metabolism and the lysophosphatidic acid (LPA) signaling pathway, and is involved in processes related to tumors, inflammatory responses, and hereditary hair disorders." (PMID 40832467, 2025).
autosomal recessive hypotrichosis (2 papers, 2022 to 2025). "Additionally, mutations in LPAR6, LIPH, and DSG4 genes have been identified in patients with autosomal recessive hypotrichosis with similar presentations." (PMID 39845463, 2025). "In addition, three new genes were identified in patients with autosomal recessive hypotrichosis, including DSG4 mapped to 18q12,1, LIPH to 3q27.3, and P2RY5 to 13q14.11-13q21.33." (PMID 36685177, 2022).
Hypertension (2 papers, 2021 to 2024). The presence of chronic increased pressure in the systemic arterial system. "LIPH (lipase member H), which belongs to the triglyceride lipase family, is involved in several diseases such as hypotrichosis/woolly hair, energy metabolism, and hypertensive disorder." (PMID 34732125, 2021).
lipid metabolism disorder (2 papers, 2023 to 2025). "It is well known that LIPH dysfunction contributes to lipid metabolism disorder." (PMID 37990271, 2023). "Although no direct studies have yet confirmed the role of LIPH in adenomyosis, lipid metabolism disorder is considered a key feature of the disease." (PMID 40832467, 2025).
lung carcinoma (2 papers, 2015 to 2016). "Lipase H (LIPH), which is selectively upregulated in lung cancer and associated with increased survival in lung cancer patients, was upregulated 13.7-fold at 37°C compared to 12°C." (PMID 27023475, 2016). "LIPH was also found to be higher expressed in the serum of lung cancer patients." (PMID 25923053, 2015).
adenomyosis (1 paper, 2025). The growth of endometrial tissue inside the muscular wall of the uterine corpus. "To thoroughly investigate potential associations between immune cell infiltration and diagnostic biomarkers in adenomyosis, we systematically analyzed the correlations between 28 immune cell types and three diagnostic markers (LIPH, CYP2E1, and CHRNE)." (PMID 40832467, 2025). "Through bioinformatics analysis, this study identified three key genes closely associated with adenomyosis: LIPH, CYP2E1, and CHRNE." (PMID 40832467, 2025). "We hypothesize that LIPH may contribute to adenomyosis development by regulating lipid metabolism pathways." (PMID 40832467, 2025).
bronchioloalveolar carcinoma (1 paper, 2015). A well or moderately differentiated morphologic variant of lung adenocarcinoma characterized by tumor growth along the alveolar structures without stromal, vascular, or pleural invasion. "Based on a microarray data survey, LIPH has been recently discovered as a putative biomarker for lung adenocarcinomas and bronchioloalveolar carcinomas." (PMID 25923053, 2015).
hypotrichosis simplex (1 paper, 2022). Hypotrichosis simplex (HS) or hereditary hypotrichosis simplex (HHS) is characterized by reduced pilosity over the scalp and body (with sparse, thin, and short hair) in the absence of other anomalies. "Several genes have been identified as being associated with hypotrichosis simplex, including LPAR6, LIPH, and DSG4." (PMID 36685177, 2022).
pancreatic adenocarcinoma (1 paper, 2024). "Lipase member H (LIPH)—a PLA1α class enzyme—produces LPA, which activates LPAR/PI3K/AKT/HIF1α signalling to promote pancreatic adenocarcinoma (PDAC) cell colony formation and proliferation." (PMID 38607068, 2024).
pancreatic ductal adenocarcinoma (1 paper, 2023). An infiltrating adenocarcinoma that arises from the epithelial cells of the pancreas. "Previous study shows that LIPH was found to be a potential gene related to poor prognosis with pancreatic ductal adenocarcinoma (PDAC)." (PMID 37990271, 2023).
tumor (11 papers, 2010 to 2025). "Furthermore, we investigated the potential mechanisms underlying the regulatory effect of LIPH on the key processes of tumour metastasis, such as cell‐cell adhesion, EMT, and mitochondrial metabolism." (PMID 32618099, 2020). "Multivariate Cox regression analysis identified LIPH expression and tumor recurrence as independent predictors of overall survival in patients with PDAC." (PMID 37990271, 2023). "RNA sequencing and immunoprecipitation showed that LIPH participates in tumor glycolysis by stimulating LPA/LPAR axis and maintaining aldolase A (ALDOA) stability in the cytosol." (PMID 37990271, 2023). "IHC staining of PDX xenograft tumor samples confirmed the pathological diagnosis and showed high LIPH expression in both." (PMID 37990271, 2023). "LIPH was positively expressed in 89 out of 139 (64.03%) IDC specimens and predominantly expressed in the cytoplasm of tumour cells compared to weak expression of LIPH in 1 out of 5 (20%) DCIS specimens (P = 0.066)." (PMID 32618099, 2020). "Collectively, these data indicate that LIPH silencing attenuated adhesion between tumour cells and suppressed the EMT process in MDA‐MB‐231 cells." (PMID 32618099, 2020). "LIPH showed significantly higher expression in metastatic samples than in primary tumours (P = 0.025)." (PMID 32618099, 2020). "LIPH suppression increased the expression of FAK p397 and paxillin, two key factors in adhesion between tumour cells, suggesting that LIPH inhibits the adhesion between tumour cells and promotes EMT through CAPN2 regulation." (PMID 32618099, 2020). "We found that LIPH silencing significantly attenuated adhesion between tumour cells by modulating the FAK p397‐paxillin signalling axis in MDA‐MB‐231 cells." (PMID 32618099, 2020). "Tandem mass spectrometric analysis presented 68 proteins were differentially expressed in LIPH‐silenced cells and LIPH‐mediated modulation of tumour cell adhesion depended on integrin‐related CAPN2 and paxillin signalling." (PMID 32618099, 2020). "We further employed Western blot analysis to verify whether LIPH silencing could affect the adhesion between tumour cells." (PMID 32618099, 2020). "Interestingly, we found a high frequency of CD44+/CD24− BCSCs in LIPH + TNBC tumours, where LIPH silencing decreased the ratio of CD44+/CD24− stem‐like cells in vitro and blocked their mammosphere‐forming ability." (PMID 32618099, 2020). "LIPH inhibited adhesion between tumour cells and enhanced the epithelial‐mesenchymal transition." (PMID 32618099, 2020). "LIPH (Lipase H), a membrane-associated phosphatidic acid-selective phospholipase A1a, is able to maintain the stability of ALDOA through activation of the LPA/LPAR axis, and directs ALDOA stability, directly connects PDAC cells to the tumor microenvironment, and promotes aberrant aerobic glycolysis." (PMID 40630951, 2025). "The messenger RNA (mRNA) levels of these genes in the TCGA-GTEx cohort displayed that SPOCK2, LIPH, RARRES3, and EMP1 were significantly higher in tumor samples than in control tissues." (PMID 38535087, 2024). "LIPH directly bridges PDAC cells and tumor microenvironment to facilitate aberrant aerobic glycolysis via activating LPA/LPAR axis and maintaining ALDOA stability, which provides an actionable gemcitabine-based combination therapy with limited side effects." (PMID 37990271, 2023). "We identified a novel lncRNA, LIPH-4, which showed elevated amounts in ESCC tissues and positive correlations with increased tumor size and poor prognosis in ESCC patients." (PMID 35971159, 2022).
tumor (continued). "Moreover, high expression of LIPH in orthotopic and PDX tumour models is a biomarker of better response to gemcitabine/Ki16425/aldometanib treatments." (PMID 38607068, 2024). "Moreover, high expression of LIPH in orthotopic and patient-derived xenograft (PDX) tumour models is a biomarker of better response to gemcitabine/Ki16425/aldometanib treatments." (PMID 38607068, 2024). "The protein levels of LIPH and ALDOA in the tumor tissues were highly positively correlated." (PMID 37990271, 2023). "Given the lack of direct and effective LIPH inhibitors, a three-drug combination therapy (ki16425/aldometanib/gemcitabine, KAG) was administered to restrict tumor glycolysis and progression." (PMID 37990271, 2023).
cancer (5 papers, 2015 to 2024). A tumor composed of atypical neoplastic, often pleomorphic cells that invade other tissues. "Kaplan–Meier analysis revealed that high LIPH expression in cancer tissues was associated with poor prognosis in patients with PDAC." (PMID 37990271, 2023). "Knockdown of LIPH expression effectively promoted apoptosis of cancer cells as well as upregulation of the apoptosis-associated protein BAX, increasing chemosensitivity to high gemcitabine concentrations, whereas overexpression of LIPH reversed this effect." (PMID 37990271, 2023). "LIPH is a secreted enzyme that hydrolysis phosphatidic acid into free fatty acid and lysophosphatidic acid which is known as a ligand for a number of G protein-coupled receptors and implicated in receptor signaling in cancer." (PMID 25923053, 2015). "Serum deprivation during apoptosis suggests a potential role for LIPH in maintaining cancer cell survival by catalyzing PA in a PDAC microenvironment with extremely poor vascularization." (PMID 37990271, 2023). "LIPH knockdown significantly decreased the stem‐like cancer cell population from 41.58% to 30.34% (P = 0.001)." (PMID 32618099, 2020). "This study provides a strong foundation for the rational development of cancer immunotherapies targeting LIPH." (PMID 32618099, 2020). "LIPH silencing decreased the stem‐like cancer cell population, down‐regulating stem‐like cell markers (Sox2 and Oct‐4) in TNBC cells." (PMID 32618099, 2020). "Given the findings from the clinical samples, we hypothesized that LIPH expression would increase the cancer stem‐like cell population." (PMID 32618099, 2020). "In addition, LIPH knockdown reduced the diameter and number of cancer stem‐like cell mammospheres." (PMID 32618099, 2020). "Notably, recent studies have observed a correlation between LIPH and adenocarcinomas of the lung or oesophagus, indicating that LIPH might be involved in the metastasis of the cancers." (PMID 32618099, 2020). "In addition, the expression levels of cancer stem cell markers were decreased after LIPH knockdown." (PMID 32618099, 2020). "LIPH catalyzes the conversion of PA to LPA and facilitates cancer cell proliferation by enhancing YAP1 nuclear localization, stimulating the PI3K/AKT/HIF1A pathway, and maintaining ALDOA stability, ultimately resulting in aberrant glycolysis and tumorigenesis." (PMID 37990271, 2023). "LIPH and LAMA3 exhibited relatively higher expression in cancer cells and neutrophils." (PMID 37745080, 2023). "In this study, we found that LIPH, a membrane-conjugated enzyme that is highly expressed in PDAC cells, can convert extracellular PA to LPA and support cell proliferation by reprogramming cancer cell metabolism." (PMID 37990271, 2023). "One limitation of this study is that we do not discuss the formation and progression of cancer cells without LIPH expression, as well as corresponding target therapy." (PMID 37990271, 2023).
LIPH also shares sentences with these, for which no sentence is quoted: asthma (2 papers); adenocarcinoma (1); alopecia (1); androgenetic alopecia (1); breast tumor (1); colorectal cancer (1); Ewing sarcoma (1); glioma (1); Hepatitis (1); hepatitis B (1); hepatocellular carcinoma (1); Hypercholesterolemia (1); leukemia (1); lung adenocarcinoma (1); Macular dystrophy (1); papillary thyroid carcinoma (1); periodontitis (1); steatosis (1).